TRIM56 (tripartite motif containing 56)
Description:
E3 ubiquitin-protein ligase that plays a key role in innate antiviral immunity by mediating ubiquitination of CGAS and STING1. In response to pathogen- and host-derived double-stranded DNA (dsDNA), targets STING1 to 'Lys-63'-linked ubiquitination, thereby promoting its homodimerization, a step required for the production of type I interferon IFN-beta (By similarity). Also mediate monoubiquitination of CGAS, thereby promoting CGAS oligomerization and subsequent activation. Promotes also TNFalpha-induced NF-kappa-B signaling by mediating 'Lys-63'-linked ubiquitination TAK1, leading to enhanced interaction between TAK1 and CHUK/IKKalpha. Independently of its E3 ubiquitin ligase activity, positive regulator of TLR3 signaling. Potentiates extracellular double stranded RNA (dsRNA)-induced expression of IFNB1 and interferon-stimulated genes ISG15, IFIT1/ISG56, CXCL10, OASL and CCL5/RANTES. Promotes establishment of an antiviral state by TLR3 ligand and TLR3-mediated chemokine induction following infection by hepatitis C virus. Acts as a restriction factor of Zika virus through direct interaction with the viral RNA via its C-terminal region.
Synonyms: RNF109
Tractability: PROTAC: UniProt records ubiquitination sites on it; ubiquitination databases record sites on it; its protein half-life has been measured.
Gene: Protein-coding gene on chromosome 7 (101,085,234 to 101,097,967, forward strand). Ensembl gene ENSG00000169871.
Subcellular location: Cytoplasm
Subcellular location (Human Protein Atlas): Nucleoplasm; Cytosol
Pathways (Reactome):
Immune System: Regulation of innate immune responses to cytosolic DNA
Gene Ontology:
Molecular function: protein binding; RNA binding; ubiquitin protein ligase activity; ubiquitin-protein transferase activity; zinc ion binding
Biological process: defense response to virus; positive regulation of innate immune response; positive regulation of non-canonical NF-kappaB signal transduction; positive regulation of type I interferon-mediated signaling pathway; protein monoubiquitination; innate immune response; positive regulation of interferon-beta production; protein K63-linked ubiquitination; regulation of type I interferon production; response to type I interferon; protein ubiquitination
Cellular component: cytoplasm; cytosol; nucleoplasm
Genetic constraint (gnomAD): Loss-of-function variants: 11 observed, 18.69 expected, observed/expected ratio (o/e) 0.59, 90% interval 0.37 to 0.97. The upper end of that interval is the gene's LOEUF score, 0.97, which puts it in group 4 of 6, group 1 being the genes least tolerant of losing a copy. Missense variants: 628 observed, 674.85 expected, observed/expected ratio (o/e) 0.93, 90% interval 0.87 to 0.99. Synonymous variants: 342 observed, 298.94 expected, observed/expected ratio (o/e) 1.14, 90% interval 1.05 to 1.25.
Homologues: Orthologues: chimpanzee TRIM56 (99% identical), macaque TRIM56 (97% identical), dog TRIM56 (91% identical), pig TRIM56 (88% identical), guinea pig TRIM56 (87% identical), rat Trim56 (81% identical), mouse Trim56 (80% identical), rabbit TRIM56 (79% identical). Paralogues in human: TRIM3 (23% identical), TRIM2 (22% identical), TRIM71 (20% identical), TRIM33 (15% identical), TRIM24 (14% identical), TRIM28 (14% identical), TRIM66 (12% identical), TRIM47 (11% identical), PML (11% identical), TRIM37 (11% identical), TRIM46 (11% identical), TRIM67 (10% identical), and 68 more.
Diseases named in the same sentence as TRIM56 in open-access papers:
TRIM56 is named in the same sentence as 47 diseases in open-access papers, as found by Europe PMC text mining. Sharing a sentence is not in itself a finding about the gene and the disease. The quoted sentences say what the papers report.
viral infection (15 papers, 2016 to 2025). "Similarly, TRIM47 is involved in the innate immunity against viral infection and is associated with neuronal autophagy, while TRIM56 regulates replication of many viruses." (PMID 38731834, 2024). "In this review, we discuss recent advances in deciphering the biological functions and antiviral actions of TRIM56 in innate immunity against viral infections." (PMID 39861861, 2025). "Remarkably, depending on viral infection settings, TRIM56 either operates in a canonical, E3 ligase-dependent fashion or adopts an enzymatically independent, non-canonical mechanism to bolster innate immune signaling." (PMID 39861861, 2025). "Taken together, these observations suggest that TRIM56 participates in modulating host autophagic response during some viral infections." (PMID 39861861, 2025). "Seven of these acetylated proteins, including DDX3X, PTBD, TRIM56, IPO7, PPID, SHMT2, and ZC3HAV1, have been implicated in innate immunity and viral infection, based on functional annotation using databases such as GO Biological Process, KEGG and reactome." (PMID 39747662, 2025). "According to reported studies, TRIM56 is capable of the ubiquitination of STING under the stimulation of virus infection." (PMID 38358243, 2024). "Specifically, ectopic expression of TRIM56 in cell culture inhibits the propagation of several flaviviruses including bovine viral diarrhea virus, yellow fever, dengue and Zika viruses, human coronavirus OC43, influenza A and B viruses, and HIV." (PMID 35062293, 2022). "For example, the E3 ubiquitin ligases TRIM56 and TRIM32 catalyze the K63-linked ubiquitination of STING upon viral infection, thereby promoting STING recruitment and STING dimerization by TBK1." (PMID 35992663, 2022). "Further studies are needed to delineate the exact subcellular localization of endogenous TRIM56 protein and any alterations to it during different viral infections and in various disease settings to aid in understanding its biological functions and regulatory mechanisms." (PMID 39861861, 2025). "Enhancing TRIM56 expression or mimicking its action could lead to novel antiviral strategies, particularly against emerging viral diseases for which existing therapies are insufficient." (PMID 39861861, 2025). "The abundance of TRIM56 is modestly upregulated by viral infections and a variety of stimuli mimicking viral infection settings, including the dsRNA surrogate poly(I:C) and type I IFNs, indicating that TRIM56 is an IFN-stimulated gene (ISG), albeit only moderately IFN-inducible." (PMID 39861861, 2025). "Importantly, TRIM56 plays a crucial role in antiviral defense by either directly inhibiting viral infection or regulating the host antiviral type I IFN response through modulating the toll-like receptor (TLR) and cGAS-STING signaling pathways." (PMID 39747662, 2025). "By modulating this pathway, TRIM56 could help fine-tune immune responses to various pathogens and inflammatory stimuli beyond viral infections." (PMID 39861861, 2025). "While the physiological role(s) of TRIM56 remains unclear, emerging evidence suggests this protein participates in host innate defense mechanisms that guard against viral infections." (PMID 39861861, 2025). "Six genes were closely associated with viral infection, namely, LY6E, receptor-type tyrosine-protein phosphatase S (PTPRS), neurogenic locus notch homolog protein 3 (NOTCH3), tripartite motif containing 56 (TRIM56), ring finger protein 135 (RNF135), and growth arrest-specific 6 (GAS6)." (PMID 38169284, 2024). "Reduction of the TRIM56 gene in viral infection may lead to the unregulated generation of IFN and cytokines." (PMID 38051999, 2023). "Given the reported TRIM56-STING connection, it is tempting to ask the question of whether the reported effects of TRIM56 on autophagy in some viral infection settings stem from its modulation of STING activity, which links immune signaling and autophagic processes." (PMID 39861861, 2025).
viral infection (continued). "Although the expression of TRIM56 is ubiquitous in various tissues, it is also regulated by IFN and viral infection." (PMID 39348396, 2024). "On the other hand, TRIM56 is known as an IFN-inducible gene and a positive regulator of TLR3 which can induce interferon and proinflammatory mediators produced during viral infection." (PMID 38051999, 2023). "In the current study, we show that under viral infection conditions, UBXN3B bridges the ER protein STING and its cytoplasmic E3 ligase TRIM56 to initiate antiviral immune responses." (PMID 29899553, 2018). "In addition, TRIM56 knockdown inhibited IFN-β production in a time-dependent manner, and promoted viral infection." (PMID 39747662, 2025). "For example, G2/I2 showed hyper-editing of type 1 interferon (IFN) receptors (IFNAR1 and IFNAR2), type 1 IFN-stimulated genes (ISGs) (e.g., EIF2AK2, DDX58/RIG-1, MAVS, TRIM56, and TRIM69) and genes involved in immune responses to viral infection (EIF2AK2, DDX58/RIG-1, MAVS, CASP8, CYCS, and HMGB1)." (PMID 35406793, 2022). "Currently, it is unclear to what extent this proposed NF-κB regulation may operate in other virus infection settings, as TRIM56 has no demonstrable effect on IκBα phosphorylation, the canonical mechanism underlying NF-κB activation." (PMID 39861861, 2025).
ovarian cancer (9 papers, 2019 to 2025). A primary or metastatic malignant neoplasm involving the ovary. "Among them, only the expression of tripartite‐motif protein 25 (TRIM25) and TRIM56 predicted good survival for ovarian cancer patients." (PMID 39887931, 2025). "Trim56 and Trim16 are considered as ubiquitin ligase for vimentin to suppress ovarian cancer and lung adenocarcinoma progression, respectively." (PMID 38383479, 2024). "The tripartite motif containing 56 (TRIM56, an E3 ligase) is related to the degree of malignancy of liver, lung, hematological, and ovarian cancers." (PMID 38463397, 2024). "PCBP1 promotes ovarian cancer migration and invasion in vitro by inhibiting TRIM56 translation, reducing its protein levels, thereby inducing Vimentin expression." (PMID 36902478, 2023). "TRIM56 was lowly expressed in multiple myeloma, ovarian cancer, lung adenocarcinoma, and hepatocellular carcinoma." (PMID 36902478, 2023). "TRIM56 is an oncogene in glioma, breast cancer, and Kaposi’s sarcoma, but it is a tumor suppressor in ovarian cancer, multiple myeloma, lung adenocarcinoma, hepatocellular carcinoma, and leukemia." (PMID 36902478, 2023). "In ovarian cancer cells, E3 ubiquitin ligase TRIM56 induced the multi-ubiquitin-mediated proteasome degradation of vimentin, leading to reduced cell migration and invasion." (PMID 36631457, 2023). "The TRIM56 inhibition of ovarian cancer migration and invasion in vitro occurs via an inhibitory effect on Vimentin." (PMID 36902478, 2023). "In ovarian cancer, RNA-affinity pulldown using biotinylated TRIM56 3’-UTR combined with mass spectrometry has found PCBP1 as the most differentially binding protein." (PMID 35287546, 2022). "In ovarian cancer cells, Trim56 has been found to be the ubiquitin ligase for Vimentin and suppress tumor invasion and migration." (PMID 33046716, 2020). "PRDX6 interacts with and upregulates NNMT via preventing TRIM56‐mediated ubiquitination and proteasomal degradation, thereby activating MAPK signaling and promoting ovarian cancer progression." (PMID 39887931, 2025). "In detail, PRDX6 competitively interacts with NNMT to prevent its binding to the E3 ubiquitin ligase TRIM56, resulting in the inhibition of ubiquitin‐mediated degradation of NNMT to activate MAPK signaling pathway and promote ovarian cancer progression." (PMID 39887931, 2025). "Together, these data suggest that PRDX6 competitively interacts with NNMT to prevent TRIM56‐mediated NNMT ubiquitination, leading to NNMT upregulation in ovarian cancer cells." (PMID 39887931, 2025). "However, the detailed role of TRIM56 in cancer progression is still not clear, although some studies showed TRIM56 could suppress malignancy progression in ovary cancer and multiple myeloma." (PMID 31000690, 2019). "In conclusion, our results demonstrated that beyond its canonical enzyme activities, PRDX6 promotes the malignant progression of ovarian cancer through a nonenzymatic mechanism, by which PRDX6 interacts with NNMT and suppresses TRIM56‐mediated ubiquitination degradation of NNMT." (PMID 39887931, 2025).
glioma (7 papers, 2022 to 2024). A benign or malignant brain and spinal cord tumor that arises from glial cells (astrocytes, oligodendrocytes, ependymal cells). "Our research revealed that TRIM56 is associated with malignant biological behaviors in gliomas, such as proliferation, migration, and invasion." (PMID 38348047, 2024). "When applied to the TCGA and CGGA RNA-seq datasets, TRIM56 exhibited a significant association with glioma grades, IDH mutation status and codeletion of chromosomes 1p and 19q." (PMID 38348047, 2024). "Here, we analyzed the relationship between TRIM family member expression and glioma prognosis in TCGA, CGGA_mRNA-array_301, and REMBRANDT datasets and found that TRIM56 upregulation was linked to poor prognosis in glioma patients." (PMID 36870986, 2023). "Herein, we identified TRIM56 as a ubiquitin ligase that is upregulated in glioma and significantly associated with a poor prognosis." (PMID 36870986, 2023). "In our study, we found that TRIM56 expression was elevated in gliomas and associated with poor survival of glioma patients." (PMID 36471347, 2022). "We determined whether TRIM56 expression was associated with immune cell infiltration in gliomas by calculating the relationship between TRIM56 expression level and the marker genes of each immune-infiltrating cell using the ssGSEA algorithm." (PMID 38348047, 2024). "In conclusion, TRIM56 is associated with glioma proliferation and invasion in addition to immunity." (PMID 38348047, 2024). "In addition to TRIM56, we included common clinical glioma diagnostic factors such as age, gender, grade, IDH mutation status, and 1p/19q co-deletion." (PMID 38348047, 2024). "High TRIM56 expression is associated with a poor prognosis in glioma patients." (PMID 36902478, 2023). "Therefore, we explored the potential association between TRIM56 and glioma immune infiltration." (PMID 38348047, 2024). "Therefore, we speculated that glioma cells with high expression of TRIM56 had a certain diagnostic value for the prognosis of glioma patients." (PMID 38348047, 2024). "Taken together, the data from this assay support that TRIM56 interacts with cIAP1 via the functional region between amino acids 21–205 (zinc finger domain), thereby inhibiting K48-linked polyubiquitination of cIAP1, reducing cIAP1 degradation and promoting glioma development." (PMID 36471347, 2022). "The results showed that gliomas consisted most of C4 (lymphocyte depleted) and C5 (immunologically quiet), C4 subtype had a worse prognosis than C5 subtype, and we observed that TRIM56 was significantly higher in C4 than C5 subtype." (PMID 38348047, 2024). "In conclusion, this is the first study to investigate the gene expression, clinical features and biological functions of TRIM56 in gliomas by bioinformatics analysis techniques including bulk RNA-seq analysis and single-cell analysis." (PMID 38348047, 2024). "In order to better evaluate the effect of TRIM56 high expression subsets on the prognosis of glioma, we established gene signature for glioma using marker genes of TRIM56 high expression subsets." (PMID 38348047, 2024). "TRIM56 expression had the highest correlation with the level of immune infiltration of macrophages in glioma, and we obtained the same results in TCGA and CGGA databases." (PMID 38348047, 2024). "EdU assay and scratch assay were used to detect the effects of TRIM56 overexpression on the proliferation, migration and invasion of glioma cells." (PMID 38348047, 2024). "At the same time, our results also indicated that with the increase of tumor grade, the correlation between TRIM56 and tumor purity also increased, which meant that the expression of TRIM56 in glioma cells also increased." (PMID 38348047, 2024). "We identified a subgroup of glioma cells with elevated TRIM56 expression, showing increased secretion of VEGF and MIF proteins compared to other subgroups." (PMID 38348047, 2024).
glioma (continued). "We found that in gliomas, tumor purity was negatively correlated with TRIM56 content, but positively correlated with immunoscore." (PMID 38348047, 2024). "We explored the differential expression of TRIM56 in various glioma subtypes and verified its role as an independent prognostic factor in gliomas." (PMID 38348047, 2024). "Taken together, TRIM56 plays a key role in glioma proliferation, migration, invasion and cell cycle." (PMID 38348047, 2024). "In order to better study the effect of TRIM56 high expression glioma cells on the tumor microenvironment, we downloaded the single cell data of GES182109 for further study." (PMID 38348047, 2024). "Pan-cancer analysis also confirmed our conjecture, but TRIM56 in glioma obtained a completely different result." (PMID 38348047, 2024). "TRIM56 is elevated in human glioma and its product stabilizes cIAP1 protein via deubiquitination, thereby inhibiting apoptosis and promoting GBM cell proliferation." (PMID 38230206, 2024). "The results showed that TRIM56 expression level was positively correlated with M2 macrophage infiltration level in glioma." (PMID 38348047, 2024). "In the previous study, it was observed that the expression of TRIM56 in tumor cells correlated positively with glioma grade." (PMID 38348047, 2024). "To comprehensively assess the impact of TRIM56 on the glioma microenvironment, we utilized single-cell analysis." (PMID 38348047, 2024). "The KEGG results suggested that TRIM56 played a role in the activation of PI3K-AKT pathway in glioma and “IL6-JAK-STAT3 signaling” gene set was enriched by GSEA analysis." (PMID 38348047, 2024). "By co-culturing M0 macrophages with glioma cells and TRIM56 overexpressing glioma cells, and verified by flow cytometry, we found that macrophages in TRIM56 overexpression group were significantly polarized to M2 macrophages compared with the control group." (PMID 38348047, 2024). "In conclusion, our study demonstrates that TRIM56 serves as a reliable immune-related prognostic biomarker in glioma." (PMID 38348047, 2024). "In this study, we investigated the relationship between the expression of the TRIM56 gene and its prognostic value in pan-cancer, identifying TRIM56 expression as an adverse prognostic factor in glioma patients." (PMID 38348047, 2024). "Our study identified TRIM56 as a glioma-favoring factor that promotes the motility of glioma cells in vitro and in vivo by potentiating CDC42 activation in an IQGAP1-dependent manner." (PMID 36870986, 2023). "TRIM56 protein expression level in glioma samples have been reported to be correlated with the WHO classification of glioma grades." (PMID 36870986, 2023). "To determine the functions of TRIM56 in gliomas with improved accuracy, we established TRIM56-knockdown and corresponding control U251 cells to explore global gene expression changes via mRNA-seq analysis." (PMID 36870986, 2023). "Using a series of clinical glioma specimens, we found the same expression features of TRIM56 at both the mRNA and protein levels in glioma." (PMID 36870986, 2023). "CDC42 knockdown or treatment with the CDC42 specific inhibitor ZCL278 reversed the enhanced migration and invasion abilities of glioma cells under TRIM56 overexpression in U87, U251 and LN229 cells." (PMID 36870986, 2023). "We used mouse glioma models as well as clinical imaging data and tumor specimens to study the role of TRIM56 in glioma migration and invasion, which is highly logical and persuasive." (PMID 36870986, 2023). "In conclusion, we elucidated the functional role of TRIM56 in promoting the motility of glioma cells via the IQGAP1-CDC42 pathway." (PMID 36870986, 2023). "This is believed to be the primary mechanism through which TRIM56 activates CDC42 to enhance glioma cell migration and invasion." (PMID 36870986, 2023). "IHC and Western blot analyses of clinical glioma tissue samples revealed a strong positive correlation between TRIM56 and IQGAP1 expression at the protein level." (PMID 36870986, 2023).